RNU1-123P (RNA, U1 small nuclear 123, pseudogene)
Gene: Small nuclear RNA gene on chromosome 16 (67,390,691 to 67,390,850, reverse strand). Ensembl gene ENSG00000239194.
Homologues: Orthologues: chimpanzee U1 (97% identical), macaque U1 (90% identical), guinea pig U1 (62% identical), dog U1 (59% identical). Paralogues in human: RNU1-1 (73% identical), RNU1-2 (73% identical), RNU1-27P (73% identical), RNU1-28P (73% identical), RNU1-3 (73% identical), RNU1-4 (73% identical), RNU1-67P (73% identical), RNVU1-18 (73% identical), RNVU1-2 (73% identical), RNVU1-29 (73% identical), U1 (73% identical), RNU1-89P (72% identical), and 133 more.